CRP (C-reactive protein)
Diseases named in the same sentence as CRP in open-access papers (continued):
Sharing a sentence is not in itself a finding about the gene and the disease.
COVID-19 (continued). "COVID-19 patients with severe CT manifestations, disease progression and need for ICU have significantly higher troponin levels in addition to elevations in ferritin, D-dimer LDH and CRP suggesting the use of troponin levels in the risk stratification of COVID-19 patients." (PMID 33501850, 2021). "Moreover, the CRP–ADC associations in the anterior corona radiata and the external capsule highlighted by our analyses are consistent with previous research conducted on COVID-19 patients." (PMID 34709472, 2021). "Elevated CRP is highly associated with the aggravation of non-severe COVID-19 adult patients." (PMID 34848761, 2021). "Increased initial CRP value (> 10 mg/L) was associated with higher odds of AKI [2.05 (1.07–3.95)] in patients with other diagnoses but did not become significant in patients with COVID-19 [2.28 (0.97–5.36)]." (PMID 33751497, 2021). "For example, Diagnosis and Treatment Protocol of COVID-19 (Trial Version 7) released on 4 March 2020 specifies clinical early-warning indicators of severe and critical cases for the first time; these indicators include cytokines, interleukin 6, and C-reactive protein." (PMID 34488797, 2021). "Interestingly, NfL concentrations were not correlated with CRP and ferritin, often found to be associated hyperinflammation in COVID-19 patients, suggesting that the raised NfL concentrations merely reflect enhanced inflammation." (PMID 33743046, 2021). "The high amounts of CRP could have an additional influence on blood pressure in severe COVID-19." (PMID 33679775, 2021). "For example, concentration of 100 mg/L of CRP has been described to implicate increased risk of ICU, prolonged length of stay, and an increase at one-month mortality; in other observational studies, serum levels of CRP allowed the researchers to recognize alarming cases of COVID-19." (PMID 33430129, 2021). "Severe COVID-19 is characterized by a marked hyperinflammatory response resulting in a cytokine storm, with dysregulated production of proinflammatory cytokines (e.g., IL-1β and IL-6), resulting in significant lymphopenia, C-reactive protein increase, and a profound vascular dysfunction." (PMID 34903264, 2021). "The results showed that five clinical features at admission, including lymphocyte (%), neutrophil count, C-reactive protein, lactate dehydrogenase, and α-hydroxybutyrate dehydrogenase, could be used for mortality prediction of COVID-19 patients with more than 91% accuracy and 99% AUC." (PMID 34541519, 2021). "In addition, the latest research evidence showed that patients who had recovered from COVID-19 had cognitive dysfunction, which may be related to the concentration of CRP inflammatory factors." (PMID 35069415, 2021). "We describe the CT features of the cerebrovascular complications of COVID-19, as well the demographic characteristics and clinical features, together with the results of laboratory tests, such as complete blood cell count, coagulation testing, renal function testing, and C-reactive protein assay." (PMID 34602662, 2021). "Moreover, recent data indicate that patients with high CRP levels, together with elevated IL-6 and PCT, are more likely to experience severe complications due to the cytokine storm associated with coronavirus disease (COVID-19)." (PMID 33790693, 2021). "Furthermore, age (OR 1.05; p=0.047), presence of comorbidity (OR 8.471; p=0.004), high NLR, LDH (final outcome) (OR 1.361 and 1.018; p<0.05), and CRP levels (midpoint) (OR 1.631; p=0.05) were identified as the strong predictors of death among COVID-19 patients." (PMID 34084685, 2021). "However, despite these limitations, our study demonstrated that both CRP and D-dimer levels may be useful predictors for in-hospital mortality rates in COVID-19 patients with pre-existing CVD." (PMID 34300252, 2021).
COVID-19 (continued). "Additionally, ferritin and C-reactive protein appear to be screening tools for the early diagnosis of a systemic inflammatory response syndrome in patients with a severe form of COVID-19 (denominated CSS), with lower cost and wider availability in frontline clinical practice than IL-6." (PMID 34185801, 2021). "Several biomarkers of inflammation and hypercoagulability, including C-reactive protein (CRP), N-terminal pro-type natriuretic peptide (NT-proBNP), Lactate dehydrogenase (LDH), procalcitonin, NLR, ferritin, troponin, and D-dimer have been associated with COVID-19 severity." (PMID 33546750, 2021). "Furthermore, a two-indicator (CRP and D-dimer) prognostic signature in training and testing datasets was constructed and validated to better understand the prognostic role of the indicators in COVID-19 patients." (PMID 34778296, 2021). "It was also found that the inflammatory factors IL-2R, IL-6, and C-reactive protein (CRP) were elevated in COVID-19 patients, and IL-2R and IL-6 had certain advantages in predicting the severity of the disease compared with traditional indicators (lymphocyte count and CRP)." (PMID 34164371, 2021). "In addition, studies have shown that c-reactive protein (CRP), interleukin-6(IL-6), D-dimer and hepatic cytokines (HGF) and C-X-C motif chemokine 13 (CXCL13) are associated with the occurrence of pulmonary fibrosis in patients with COVID-19." (PMID 35069217, 2021). "A retrospective single-center study with 600 COVID-19 patients in the United States reported hypertriglyceridemia as being associated with mortality (OR, 2.3; 95% CI, 1.4–3.7; P = 0.001) independent of obesity, high CRP, and high leukocyte count." (PMID 34774031, 2021). "COVID-19 patients with severe disease exhibit higher levels of monocyte counts and higher frequencies of classical monocytes and lower frequencies of intermediate and non-classical monocytes and elevated plasma levels of sCD14, CRP, sCD163 and sTF in comparison with mild disease." (PMID 34642411, 2021). "Also, dexamethasone therapy resulted in markedly reduced CRP levels in COVID-19 patients." (PMID 34353339, 2021). "The levels of IL-8, IL6, and CRP were elevated above the normal range in both survived and deceased patients; however, all three inflammatory markers were approximately 2-4-fold higher in deceased COVID-19 patients compared to patients who recovered (p<0.0001)." (PMID 34228746, 2021). "One could argue that more quantifiable physiological and blood test parameters might have expressed COVID-19 severity more adequately, i.e., temperature, blood pressure, heart rate, hemoglobin, thrombocytes, leukocytes, creatinine, lymphocytopenia, C-reactive protein, and procalcitonin." (PMID 34529732, 2021). "The CRP, significantly elevated in the non-survivors compared with the survivors [52.38 (7.76~132.7) vs. 2.46 (0.92~10.07) mg/L], was an independent risk factor for mortality of COVID-19." (PMID 34733858, 2021). "Therefore, in addition to prior known biomarkers (e.g., procalcitonin, CRP, lymphocyte count, D-dimer, troponin I, AST, ALT, among others) associated with severe COVID-19, serum albumin levels might help in prognostic risk stratification." (PMID 33725003, 2021). "COVID-19 is accompanied by the activation of the immune system and the elevation of inflammatory cytokines, such as C-reactive protein, ferritin, and interleukin-6 (IL-6), and could induce a severe catastrophe response with hyperinflammation, namely, the “cytokine storm”." (PMID 34623311, 2021). "Similarly, Chen reported that in critical and severe patients with COVID-19, the markers of myocardial injury and inflammation including TNI, N-terminal probrain natriuretic peptide (NT-proBNP), and high-sensitivity CRP were significantly elevated and associated with mortality." (PMID 34725560, 2021). "Accordingly, CRP levels may be of value for monitoring the COVID-19 disease, once developed." (PMID 35011944, 2021).
COVID-19 (continued). "Nevertheless, CRP and ferritin were markedly elevated in patients at the start of therapy, consistent with levels observed in aggregated data from multiple studies of severe COVID-19 correlating high inflammatory markers with worse outcomes, and the levels decreased with CytoSorb therapy." (PMID 34988092, 2021). "CRP testing may be useful in the initial evaluation of COVID-19 patients." (PMID 33727641, 2021). "In line with this, COVID-19 sera were found to contain abundant NETosis markers such as cell-free DNA, myeloperoxidase- (MPO-) associated DNA, and citrullinated histone H3 (citH3), together with elevated levels of the acute-phase C-reactive protein (CRP) and D-dimer." (PMID 34367376, 2021). "Here, the elevation of CRP above 35 mg/L is certainly not credible as a diagnostic marker of COVID-19 but may be considered as a useful prognostic marker for severe forms of COVID-19, even in older adults." (PMID 34506514, 2021). "Therefore, it remains unclear whether the elevation of CRP in the early stages of COVID-19 could serve as a prognostic marker in patients with COVID-19, especially in the group of older adults." (PMID 34506514, 2021). "In conclusion, ferritin, D-dimer, CRP, NLR, cytokines (IL-6, IL-18, and IL-10), and cytokine receptors (IL-1Ra and sIL-2rα [sCD25]) in combination with clinical information may aid the early identification of patients at risk of critical COVID-19." (PMID 34422145, 2021). "A study conducted on four COVID-19 patients with coexisting ischemic stroke has shown an elevated D-diameter (a lab test that measures fibrin degradation fragments) and C-reactive protein level (CRP, a protein produced by the liver in response to inflammation)." (PMID 34901061, 2021). "They authors of the study suggested that circulating lymphocytes, CRP, procalcitonin, IL-6, and viral load could serve as predictors for disease typing and guide classification of COVID-19 patients, and that circulating lymphocytes was the most reliable and sensitive predictor biomarker." (PMID 35174189, 2021). "Thus, CRP may be one of the prognostic tools that predicts the morbidity of the COVID-19 course, but only in severe cases." (PMID 35011944, 2021). "This study showed that the CRP level in patients with moderate COVID-19 was significantly higher than that in patients with asymptomatic COVID-19 (the difference was significant), suggesting that CRP may be used to predict the presence of clinical symptoms of COVID-19." (PMID 34722325, 2021). "However, the lupus anticoagulant testing might be interfered by heparin use or elevated C-reactive protein in COVID-19 patients." (PMID 33777042, 2021). "COVID-19 patients groups displayed diverse clinical manifestations, but all the patients showed at least two of the commonly reported symptoms, and the severe COVID-19 group showed high levels of breathing frequency, low oxygen saturation, and high levels of C-reactive protein (CRP) and fibrinogen." (PMID 34445140, 2021). "Furthermore, our findings suggest that specific laboratory markers ferritin, ALT, urea, and CRP may be indicative of COVID-19 severity although large prospective studies are needed for identifying these variables as predictor factors." (PMID 34621457, 2021). "Another study of 12 patients with neurological complications presenting with post-COVID-19 symptoms between 9 and 12 weeks post-onset found an acute inflammatory phase with significantly elevated inflammatory parameters including C-reactive protein CRP and IL-6 levels." (PMID 34685427, 2021). "Moreover, C-reactive protein levels may predict the occurrence of venous thromboembolism in critically ill COVID-19 patients admitted to the ICU with an AUC of 0.75; for comparison, the AUC of the D-dimer in this study was only 0.64." (PMID 34441957, 2021).
COVID-19 (continued). "However, both of these findings are commonly present in patients with COVID-19.17, 18 In a Scottish survey, C-reactive protein levels of at least 100 mg/L and chronic obstructive pulmonary disease or chronic lung disease were positively associated with antimicrobial prescribing." (PMID 34100002, 2021). "The emerging evidence suggests that patients who develop COVID-19 complications have an abnormal immune response, which includes lymphocytopenia (in ~83%), thrombocytopenia (in ~36%), leukopenia (in ~33%), and elevated levels of c-reactive protein (CRP, in ~58%)." (PMID 34639569, 2021). "In a study of 494 KTRs, elevations of inflammatory markers (CRP, lactate dehydrogenase-LDH, and procalcitonin), cardiac injury markers (hs-troponin I), and thrombosis markers (D-dimers) were significantly associated with a higher risk of COVID-19-related mortality." (PMID 34578460, 2021). "Viewed altogether, the findings from this exploratory clinical study suggest that early monitoring of two key predictors of lung abnormalities, namely, circulating levels of CRP and albumin, may permit early therapeutic interventions to avoid or limit COVID-19 progression." (PMID 33396578, 2020). "Here we combine VitD and high-sensitivity CRP (hs-CRP) data from NHANES, 2009–2010 dataset with clinical data from COVID-19 patients to assess a possible role of VitD in regulating inflammation and cytokine production which is a major risk factor for severe COVID-19 across different countries." (PMID 32876941, 2020). "The findings of this study indicate that the integration of NLR and CRP may lead to improved prediction and is thus recommended as a valuable early marker to assess prognosis and evaluate the severity of clinical symptoms in COVID-19 patients." (PMID 33244379, 2020). "Interestingly, ACEi/ARB-treated COVID-19 positive patients displayed lower concentrations of CRP and procalcitonin, suggesting that the benefit of ACEi and ARB might rely on their anti-inflammatory effects." (PMID 32848769, 2020). "However, the NRI adjusted for CRP level remained associated with severe COVID-19, meaning that neither inflammation nor age entirely explained the association." (PMID 33260603, 2020). "Moreover, Multivariate analysis showed that hemoglobin level (OR, 0.89; 95% CI, 0.81–0.98; p = 0.022), neutrophil counts (OR, 1.80; 95% CI, 1.09–2.97; p = 0.021), and CRP (OR, 1.04; 95% CI, 1.001–1.071; p = 0.043) levels were found to be independent predictors of COVID-19 severity." (PMID 33192519, 2020). "Amongst the participants hospitalized with COVID-19, we report that a higher prevalence of detectable SARS-CoV-2 plasma viral load is associated with worse respiratory disease severity, lower absolute lymphocyte counts, and increased markers of inflammation, including C-reactive protein and IL-6." (PMID 33127906, 2020). "The most recent COVID-19 diagnosis and treatment program (7th edition) published by the National Health Commission of China suggested using indicators such as low lymphocyte counts, high levels of CRP, ESR, CK, AST, and LDH, and high levels of cytokines in severe patients." (PMID 33251228, 2020). "COVID-19 was severe in patients with hematological malignancies, and their survival was strongly correlated with the COVID-19 stage and patient and disease-related factors [older age, disease status, performance status, immune (neutropenia) status and systemic inflammation (high CRP)]." (PMID 32864192, 2020). "AST [27.0 (20.0–40.0) vs. 24.0 (18.0–38.0), p = 0.008], LDH [258.0 (200.0–355.0) vs. 227.0 (181.0–309.0)], CRP [30.8 (9.4–68.9) vs. 9.4 (2.4–54.1), p < 0.001] and procalcitonin [0.06 (0.04–0.14) vs. 0.05 (0.03–0.09), p < 0.001] were substantially higher in the COVID-19 patients with GI symptoms." (PMID 33262996, 2020).
COVID-19 (continued). "Interestingly, We found that cTnI was strongly positively correlated with CRP (r = 0.704, p = 0.042) and LDH (r = 0.738, p = 0.037), and related literature had reported that both LDH and CRP can be used as powerful predictors for early identification of patients with severe COVID-19." (PMID 33334317, 2020). "However, in the present study, which compared COVID-19 cases with other febrile illnesses and cases with abnormal images on chest CT, a low level of procalcitonin was evident in patients with COVID-19, whereas the CRP level was elevated." (PMID 33208116, 2020). "C-reactive protein (CRP) may further enhance the localised deposition of complement in the vessel wall, since gross elevation of CRP occurs in the acute phase of Kawasaki disease (and COVID-19) and this protein can mediate classical pathway activation of complement." (PMID 33584675, 2020). "Finally a systematic review on the role of biomarkers in COVID-19, which looked at 26 different articles, concluded that IL-6 CRP, LDH, D-dimer, troponin, blood urea nitrogen and creatinine were elevated while leukocyte count is decreased in patients with severe SARS-CoV-2 infection." (PMID 32992775, 2020). "A study of 74 COVID-19 patients reported that surviving patients had significantly higher H2S levels than non-survivors, and that serum H2S levels negatively correlated with serum IL-6, CRP, and procalcitonin (markers for bacterial infection, sepsis, and tissue injury)." (PMID 33330130, 2020). "In this study, fevered COVID-19 patients had a stronger inflammatory response than non-fevered patients, manifested by significantly increased erythrocyte sedimentation rate and CRP, which may be the reason for the higher proportion of severe patients in fevered COVID-19 patients." (PMID 32719804, 2020). "Lymphocytopenia, increased C-reactive protein, and increased aPPT have an unfavorable prognostic value that could lead to an increased risk for severe COVID-19 forms in nonpregnant adults." (PMID 32633712, 2020). "The study also showed that dexamethasone should only be used in severe COVID-19 patients with CRP levels above 20 mg per deciliter of blood, and the use of dexamethasone should be avoided in COVID-19 patients (under ventilator support) with CRP level below 10 as it may turn out to be fatal." (PMID 32973505, 2020). "Adult fevered COVID-19 patients presented a higher risk of developing severe events compared to non-fevered patients, while CRP and lymphocyte proportion may be effective predictive factors." (PMID 32719804, 2020). "Those patients generally present an increase in COVID-19-associated inflammatory markers, such as d-dimer, leukocytes count, neutrophil count, neutrophil-to-lymphocyte (NTL) ratio, alanine aminotransferase (ALT), aspartate aminotransferase (AST), and c-reactive protein (CRP)." (PMID 33584342, 2020). "Clinical markers such as C-reactive protein (CRP), Interleukin 6 (IL-6), and erythrocyte sedimentation rate (ESR) were found to be increased in severe COVID-19 cases." (PMID 41557029, 2026). "In this study, the analysis of inflammatory markers (CRP, IL-6, PCT), an early warning signal of severe COVID-19 (NLR), an indicator of disease severity (eosinophils), and monocyte data in patients was performed." (PMID 40284583, 2025). "The levels of D-dimer, LDH, CRP, NLR, and ferritin reflect the degree of systemic tromboinflammation and disease severity in COVID-19 patients." (PMID 40342417, 2025). "Our study reveals that elevated levels of inflammatory markers (CRP and LDH) and a reduction in platelet count are correlated with increased severity of COVID-19." (PMID 40901150, 2025). "Readily available laboratory parameters, such as leukocyte count, lymphocyte count, C-reactive protein (CRP), liver enzymes, and serum creatinine, have been studied for their prognostic value in COVID-19." (PMID 40428888, 2025).